SRD5A2 (steroid 5 alpha-reductase 2)
Diseases named in the same sentence as SRD5A2 in open-access papers (continued):
Sharing a sentence is not in itself a finding about the gene and the disease.
5-alpha reductase deficiency (3 papers, 2016 to 2025). "In conclusion, we believe that this is the first report on an extended family with 5-alpha reductase deficiency caused by a novel deletion of exon 2 of the SRD5A2." (PMID 27086719, 2016). "These include three patients (i.e., P09, P22, P28) with 5-alpha-reductase deficiency due to biallelic mutations of the SRD5A2 gene, and four patients with idiopathic hypogonadotropic hypogonadism due to mutations of KAL1 (i.e., P27, P32), PROKR2 (P03) or GNRHR (P13)." (PMID 28295047, 2017).
Micropenis (3 papers, 2014 to 2024). "Interestingly, two patients (DSD-0249 and DSD-0278) diagnosed with micropenis carry only one heterozygous variant of SRD5A2 gene, with no additional pathogenic variants identified, which cannot explain the phenotype." (PMID 39285472, 2024).
acne (2 papers, 2015 to 2021). An inflammatory process of the sebaceous glands which is characterized by comedones, nodules, papules and/or pustules on the skin. "In addition, the following variants were significantly associated with acne risk: ADH7 (alcohol dehydrogenase 7) rs1154469, SRD5A2 (steroid 5 alpha-reductase 2) TA repeat VNTR and VDR (vitamin D receptor) rs731236 and rs7975232." (PMID 33849530, 2021).
alopecia (2 papers, 2022 to 2026). Hair loss usually from the scalp. "Excessive production of DHT by SRD5A2, which is a representative cause of male pattern hair loss, induces the expression of DKK1, an inhibitor of the Wnt signaling pathway, via AR stimulation, which ultimately leads to the blockade of the Wnt signaling pathway." (PMID 35784391, 2022). "Finasteride, the most effective chemical drug available at present for treating hair loss, inhibits the conversion of testosterone to DHT by inhibiting the activity of SRD5A2, thereby inducing hair growth and slowing the progression of hair loss." (PMID 35784391, 2022).
breast carcinoma (2 papers, 2012 to 2025). "SRD5A1 and SRD5A2 are also consistently over-expressed in breast cancer, which increases the levels of progesterone metabolites possibly involved in cell proliferation." (PMID 22257483, 2012).
depression (2 papers, 2019 to 2025). "However, a previous study found that the altered methylation level of the SRD5A2 gene in the cerebrospinal fluid may contribute more to the potentially causal effect of finasteride on depression." (PMID 41330881, 2025). "We compared SRD5A1 and/or SRD5A2 promoter methylation in DNA samples obtained from blood and/or CSF in PFS patients and controls and correlated the resulting epigenetic pattern with the neuroactive steroid levels previously found by us to be associated with major depression and sexual side effects." (PMID 31272082, 2019).
disorders of sex development (2 papers, 2022 to 2025). "In this study, we present the clinical, laboratory, and genetic characteristics of patients diagnosed with SRD5A2-associated 46,XY disorders of sex development (DSD), along with the decisions made by the Multidisciplinary Gender Assessment Committee (GAC)." (PMID 40381132, 2025). "46,XY disorders of sex development (DSDs) are caused by abnormalities in more than 60 genes, with SRD5A2 pathogenic variants being one of the most common causes." (PMID 40381132, 2025). "SRD5A2 (steroid 5-alpha-reductase 2) mutation, which impairs 5α-reductase-2 enzyme activity, is among the causes of 46,XY disorders of sex development (DSD)." (PMID 35386187, 2022). "Pathogenic variants in SRD5A2 are a common cause of 46,XY disorders of sex development (DSDs)." (PMID 40381132, 2025).
liver cancer (2 papers, 2022 to 2025). An epithelial or non-epithelial malignant neoplasm that arises from the liver. "To date, some reports revealed that SRD5A2 polymorphism may be associated with liver cancer, and it might serve as a robust diagnosis or prognosis marker for the diagnosis of HCC." (PMID 35196258, 2022). "It was also found that NR1I2, SRD5A2, and SHBG may be potential down-regulated target proteins of Huachansu injection in the treatment of liver cancer." (PMID 39806972, 2025).
liver fibrosis (2 papers, 2017 to 2023). "It is of note in this study that the expression level of SRD5A2 was significantly higher in female patients aged > 50 years old compared with those aged ≤ 50 years old, while the degree of liver fibrosis was significantly more severe in the former group." (PMID 37784175, 2023). "In this study, male chronic HBV-infected patients with hepatic fibrosis at stage F4 had the T/T genotype at both the rs12470143 and rs7594951 loci of the SRD5A2 gene, and hepatic SRD5A2 protein expression was significantly elevated." (PMID 37784175, 2023). "Furthermore, the severity of liver fibrosis at the rs12470143 and rs7594951 loci of the SRD5A2 gene was compared between patients of different sexes and ages, specifically between those with the T/T genotype and those with the non-T/T genotype." (PMID 37784175, 2023). "Notably, several hormone metabolism relevant genes have been found to have a significantly negative association with liver fibrosis, including steroid 5 alpha-reductase 2 (SRD5A2), and the cytochrome P450 gene family." (PMID 28262670, 2017). "Furthermore, the severity of hepatic fibrosis was positively correlated with the level of SRD5A2 expression, suggesting that an elevated level of SRD5A2 expression may promote the development of fibrosis by reducing MMP-2 activity and impairing the degradation of extrahepatic matrix proteins." (PMID 37784175, 2023).
prostate adenocarcinoma (2 papers, 2014 to 2023). "Although at least three other activating missense substitutions have been described in SRD5A2 (p.Val3Ile, p.Phe118Leu, and p.Ala248Val), these were identified from microdissected prostate adenocarcinoma samples and were found to be somatic mutations." (PMID 25077171, 2014). "SEMA3C expression is correlated with expression of steroidogenic enzymes CYP11A1 and SRD5A2 as well as the AR target gene, FKBP5, in prostate adenocarcinoma patients according to TCGA PanCancer dataset available on cBioPortal." (PMID 37800655, 2023).
Adrenal insufficiency (1 paper, 2025). Insufficient production of steroid hormones (primarily cortisol) by the adrenal glands. "Mutations in genes related to steroid biosynthesis (such as CYP11A1, CYP17A1, HSD3B2, HSD17B3, and StAR) will lead to androgen synthesis disorders with adrenal insufficiency besides the SRD5A2 gene mutation which results in the insufficient transformation of dihydrotestosterone from testosterone." (PMID 40247401, 2025).
amenorrhea (1 paper, 2022). The absence of menses in a woman who has achieved reproductive age. "Case 29, who carries compound heterozygous variants in the SRD5A2 gene, presented at 14 years with primary amenorrhea, clitoromegaly and absence of secondary sexual characteristics." (PMID 35432193, 2022).
asthma (1 paper, 2009). "In our libraries, the expression of Srd5a2 was up-regulated in asthma but down-regulated by acupuncture." (PMID 19419550, 2009). "The changed expression suggested that Srd5a2 served as an adjustable gene target of acupuncture, which may relate with the genesis of steroid by acupuncture in the EAR phase of asthma." (PMID 19419550, 2009).
citrin deficiency (1 paper, 2025). "In this study, the four most common recessive genes of metabolism disorders were identified (> 1/60), including the SRD5A2 gene (5-alpha reductase deficiency), ATP7B gene (Wilson disease), PAH gene (Phenylketonuria), and SLC25A13 gene (Citrin deficiency)." (PMID 40447697, 2025).
development (1 paper, 2019). "In the current study, we analysed 37 subjects diagnosed with 46,XY DSD (disorders of sex development) with confirmed variations in the SRD5A2 gene." (PMID 31885560, 2019).
disorder of sexual differentiation (1 paper, 2024). A congenital disorder characterized by abnormalities in the development of the sexual characteristics. "Interestingly, a few patients with Disorders of Sexual Differentiation (DSD) shared rare pathogenic variants in the SRD5A2, HSD17B3 and HSD3B2 while patients with Glucose and Insulin Homeostasis carried theirs in GCK and HNF1A genes." (PMID 38637882, 2024).
fibrosis (1 paper, 2023). the formation of excess fibrous connective tissue in an organ or tissue in a reparative or reactive process. "Similarly, SRD5A2 protein levels were significantly greater in patients with the METAVIR fibrosis score F3–F4 compared with those with the score F0–F2 (p < 0.05)." (PMID 37784175, 2023).
Hepatic steatosis (1 paper, 2016). Steatosis is a term used to denote lipid accumulation within hepatocytes. "SRD5A1 knockout mice develop hepatic steatosis when fed an obesogenic diet, whereas SRD5A2 knockout mice do not." (PMID 26574953, 2016).
Hydrocephalus (1 paper, 2019). Hydrocephalus is an active distension of the ventricular system of the brain resulting from inadequate passage of CSF from its point of production within the cerebral ventricles to its point of absorption into the systemic circulation. "Our finding of high levels of methylated SRD5A2 in CNS cells of a normotensive hydrocephalus individual, displaying an epigenetic status at odds with all other control subjects, further supports the link between DNA methylation pattern and disorders of the nervous system." (PMID 31272082, 2019).
hypertrophy (1 paper, 2021). Hypertrophy is the increase in the volume of an organ or tissue due to the enlargement of its component cells. "For this reason, SRD5A2 has been studied as an important target in the development of many prostate hypertrophy inhibitors." (PMID 33803357, 2021).
Kallmann syndrome (1 paper, 2025). Kallmann syndrome (KS) is a developmental genetic disorder characterized by the association of congenital hypogonadotropic hypogonadism (CHH) due to gonadotropin-releasing hormone (GnRH) deficiency, and anosmia or hyposmia (with hypoplasia or aplasia of the olfactory bulbs). "In addition, genetic testing for SRD5A2 and AR abnormalities was not conducted, and with the exception of one patient diagnosed with Kallmann syndrome, the primary cause remained undetermined." (PMID 40813749, 2025).
male infertility (1 paper, 2016). The inability of the male to effect fertilization of an ovum after a specified period of unprotected intercourse. "Most SNP-populated genes related to male infertility include HLA-DQB1 (20 SNPs), HLA-DRB1 (15 SNPs), MTHFR (10 SNPs), BRCA2 (9 SNPs), ACE (8 SNPs), CFTR (6 SNPs), CDH1 (6 SNPs), SRD5A2 (6 SNPs), HLA-DQA1 (5 SNPs) and MMP9 (5 SNPs)." (PMID 29263816, 2016).
metabolic syndrome (1 paper, 2024). A cluster of metabolic risk factors for CARDIOVASCULAR DISEASES and TYPE 2 DIABETES MELLITUS. "Prior research has linked high expression of SRD5A2 to increased prostate volume and metabolic syndromes." (PMID 38778357, 2024).
metastatic disease (1 paper, 2022). "5-alpha reductase type 2 (i.e. SRD5A2) allelic variants occur with the highest frequency in African American men and are associated with increased risk of PC and are the only individual biomarker significantly associated with 5-year risk of metastatic disease." (PMID 36324578, 2022).
nonalcoholic fatty liver disease (1 paper, 2020). "Among them, SRD5A1 and SRD5A2 were reported to be highly expressed in human liver, and the protein level of SRD5A1 increased with the severity of nonalcoholic fatty liver disease (NAFLD)." (PMID 33229626, 2020).
ovarian endometriosis (1 paper, 2016). A non-neoplastic disorder characterized by the growth of endometrial tissue in the ovaries. "SRD5A1 and SRD5A2 can convert both P to 5α-dihydroprogesterone in human ovarian endometriosis and T to 5α-dihydrotestosterone in human prostate, while the function of SRD5A3 in steroid metabolism is still unclear." (PMID 27149376, 2016).
prediabetes (1 paper, 2023). "Notably, our study identified six SNPs (rs10207755, rs522638, rs523349, rs632148, rs534999, and rs558803) in SRD5A2 that showedassociations with TG levels in individuals with prediabetes." (PMID 38371897, 2023).
prostate tumor (1 paper, 2023). "It has been also demonstrated that prostate tumor cells with increased levels of SRD5A2 expression exhibit significantly reduced matrix metallopeptidase 2 (MMT2) activity compared to control cells." (PMID 37784175, 2023).
uterine cancer (1 paper, 2025). Primary or metastatic malignant neoplasm involving the uterine corpus and/or the cervix. "The ‘Genotype’ hypothesis findings for uterine cancer showed that the expression of the genes CMC2, CXCL13, CXCL19, LAG3, SRD5A2, and others had changed." (PMID 40847033, 2025).
tumor (13 papers, 2004 to 2023). "SRD5A2 was decreased in tumours and negatively associated with BCR." (PMID 30616540, 2019). "SRD5A2 was previously identified in a candidate screen of 732 PCa-related genes and forms part of the commercial Oncotype DX Genomic Prostate Score assay that predicts tumour aggressiveness in low and intermediate risk PCa." (PMID 30616540, 2019). "The findings also showed that the mRNA expression of SGPP2 was higher in tumor tissues, whereas the mRNA expression of SRD5A2 was higher in normal tissues." (PMID 36106334, 2022). "For SRD5A2, the results from four datasets showed the transcriptional level of SRD5A2 was downregulated in the tumor tissues." (PMID 36159555, 2022). "The qRT-PCR results suggested that the expression of SGPP2 was significantly elevated in tumor tissue specimens, while the expression of SRD5A2 was significantly increased in normal tissue." (PMID 36106334, 2022). "We observed decreased protein expression of SRD5A2 in advanced tumor stages (Gleason ≤ 7 vs. Gleason >7, P = 0.031, Stage I + II vs. Stage III + IV, P = 0.148, Gleason 3 + 4 vs. Gleason 4 + 3, P = 0.035)." (PMID 35293897, 2022). "The expression of SRD5A1and SRD5A2 was negatively correlated with the HCC tumor stage, and the high expression of SRD5A3 was significantly positively associated with the high tumor stage." (PMID 36159555, 2022). "Although gene expression levels were lower with OB diets, higher body weight at tumor detection increased the expression of intratumoral srd5a1 (p = 0.023) and srd5a2 (p = 0.001)." (PMID 34535690, 2021). "TP led to reduced tumor growth, intratumoral inflammation, and intratumoral androgen-regulated gene expression (srd5a1, srd5a2) when incorporated with the CON diet but greater tumor growth and intratumoral gene expression when incorporated with the OB diet." (PMID 34535690, 2021). "We revealed a negative association of SRD5A2 and tumor progression, reflected by the Gleason score (P = 0.013) and pathological tumor stage (P = 0.047)." (PMID 35293897, 2022). "Our results confirm the tumor-suppressive role of SRD5A2 and the oncogenic role of ITGA11 in PCa." (PMID 35293897, 2022). "The genes Fam65b and Il1r1 were methylated preferentially in the non-tumor liver tissue, whereas the genes Synpo and Tspan9 were methylated preferentially in tumors; the gene Srd5a2 in each half of the tested tumors was preferentially methylated in either the non-tumor tissue or in tumors." (PMID 25918251, 2015). "According to the previous literature, the positive prognostic values of ZNF185, SRD5A2, and AOX1 are expressed in normal tissues than in tumors, but their methylation levels in tumor tissues are higher than those in normal tissues." (PMID 35813821, 2022). "Indeed, the main finding of our study is that SRD5A1 and SRD5A2 decreased and SRD5A3 significantly increased in HCC tumor tissues." (PMID 36159555, 2022). "After adjusting for body weight at tumor detection, OB diets did not affect srd5a1 expression but led to significantly lower intratumoral srd5a2 (p = 0.0004) and ar (p = 0.032) expression compared with CON diets." (PMID 34535690, 2021). "Ten of 12 transcripts that were prognostic in Gleason score 7 tumours remained prognostic in patients with Gleason 3 + 4 = 7 tumours, and multivariable logistic regression analysis showed that combining CCNB1 or UBE2C with SRD5A2 slightly improved the predictive power of the model." (PMID 30616540, 2019). "Most of the validated mRNAs provided unique information about tumor aggressiveness, however, three pairs of transcripts in the validated set of 23 were correlated (P‐values < 0.05): CCNA2 and TPX2 (r2 = 0.61); SRD5A2 and DPT (r2 = 0.56); and SRD5A2 and FBLN1 (r2 = 0.73)." (PMID 28145099, 2017).
cancer (11 papers, 2001 to 2025). A tumor composed of atypical neoplastic, often pleomorphic cells that invade other tissues. "However, the implication of SRD5A2-linked genetic polymorphisms in cancer susceptibility and male sexual differentiation is complex and characterized by contradictory studies that have yet to be clarified." (PMID 40043094, 2025). "We found that the mRNA expression of IL7R, COL22A1, ZNF185, and SRD5A2 were upregulated in cancer tissues, while PTGS2 and CLDN1 were higher in normal tissues, consistent with our previous analysis." (PMID 35813821, 2022). "The level of SRD5A2 was significantly downregulated in the cancer tissues than that in normal tissues." (PMID 36159555, 2022). "The MMP2 gene expression followed exactly the opposite trend of SRD5A2, and this was consistent with data described also by other researches, where exogenous expression of SRD5A2 reduces the cell migration/invasion in cancer cells." (PMID 28489571, 2017). "The enzyme human steroid 5-α reductase type II (SRD5A2) and androgen receptor (AR) are critical mediators of androgen action, suggesting a potential role in hormonally related cancers." (PMID 11259089, 2001). "Therefore, we focused on the anti-oncogenic effects of 5α-reductase inhibition and evaluated the effects on cancer progression of the dutasteride target genes SRD5A1 and SRD5A2, encoding 5α-reductase Type 1 and 2, respectively." (PMID 36800968, 2023). "As an isoenzyme of SRD5A1 and SRD5A2, SRD5A3 has been discovered lately and it is demonstrated as an oncogene and confers a poor prognosis in several human cancers, such as breast cancer and hepatocellular carcinoma." (PMID 39680264, 2024).
genetic disorders (1 paper, 2025). "Therefore, the significant prevalence of SRD5A2 gene mutations in Vietnamese pregnant women highlights the importance of carrier screening for autosomal recessive genetic disorders." (PMID 40447697, 2025).
SRD5A2 also shares sentences with these, for which no sentence is quoted: androgenetic alopecia (3 papers); chronic hepatitis B infection (2); complete androgen insensitivity syndrome (2); androgen excess (1); autism (1); beta thalassemia (1); chronic sinusitis (1); Cirrhosis (1); diabetes (1); disorders of the nervous system (1); endocrine disorders (1); endometrial cancer (1); focal segmental glomerulosclerosis (1); Friedreich ataxia (1); Hirsutism (1); infection (1); metabolism disorders (1); neurodevelopmental disorder (1); neuropathy (1); Obesity (1); Opitz syndrome (1); partial androgen insensitivity syndrome (1); phenylketonuria (1); phimosis (1); prostatic hyperplasia (1); Simpson-Golabi-Behmel syndrome (1); thin membrane nephropathy (1); Wilson disease (1).